NEU1 (neuraminidase 1)
Diseases named in the same sentence as NEU1 in open-access papers (continued):
Sharing a sentence is not in itself a finding about the gene and the disease.
sialidosis (continued). "It is known that marked reduction in NEU1 activity, due to mutations in the gene, leads to sialidosis, an inherited disease characterized by coarse facial features, hepatomegaly, dysostosis multiplex, and developmental delay, myoclonic epilepsy, visual impairment and ataxia." (PMID 32975669, 2020). "Sialidosis is a rare autosomal recessive lysosomal storage disease (approximate prevalence of 1/5,000,000-1/1,500,000 live births) caused by a deficiency of neuraminidase (sialidase) due to mutations in the NEU1 gene located on chromosome 6p21.3." (PMID 32752208, 2020). "Sialidosis is a rare genetic lysosomal storage disease caused by mutations in the N-acetyl-alpha-neuraminidase − 1 (NEU1) gene (chromosome 6p21), encoding the lysosomal enzyme neuraminidase, which triggers the degradation of sialyloligosaccharides in lysosomes." (PMID 32867703, 2020). "These symptoms were believed to be caused by the secondary deficiency of Neu1 resulting in storage of sialylated oligosaccharides and glycopeptides, since similar ophthalmologic problems were also observed in the patients affected with a single Neu1 genetic deficiency, sialidosis (OMIM #256550)." (PMID 28234994, 2017). "In this study, the authors review the diverse roles of NEU1 in various cellular mechanisms, its potential substrates that have been reported in the literature so far, and its roles in different cellular mechanisms that have been associated with both sialidosis and AD." (PMID 35847014, 2022). "Integrating this approach with biochemical and cellular studies led us to the identification in NEU1 gene of new rare alleles carrying missense and frameshift mutations responsible for impaired enzyme activity, thus representing new putative causative mutations responsible for sialidosis." (PMID 25153125, 2014). "However, since mutation of Neu1 cause sialidosis, it is of interest to consider how potential side-effects associated with Neu1 inactivation may be avoided." (PMID 25187624, 2014). "These zebrafish also display decreased expression of genes involved in bone remodeling, mirroring the phenotypes seen in Neu1-KO mice and human sialidosis patients 46-48." (PMID 41356197, 2026). "Sialidosis is a rare autosomal recessive lysosomal storage disorder caused by mutations in the NEU1 gene, resulting in deficient neuraminidase-1 activity and the subsequent accumulation of sialylated compounds in lysosomes." (PMID 40004480, 2025). "A parallel pathway to lysosomal dysfunction can be found in Sialidosis, a rare autosomal recessive LSD caused by mutations in the NEU1 gene, leading to deficiency of lysosomal neuraminidase." (PMID 41614773, 2025). "Sialidosis is a rare cause of PME, caused by a deficiency of α-N-acetyl neuraminidase caused by mutations in the neuraminidase 1 gene (NEU1)." (PMID 38397161, 2024). "These glycoconjugates are also released by podocytes in the urine ultrafiltrate, resulting in a drastically increased concentration of sialylated oligosaccharides in the urine of patients with sialidosis and Neu1-null mice." (PMID 37698928, 2023). "The morphological and molecular phenotypes of neu1-KO fish are rather similar to those detectable in Neu1-KO mice and in patients affected by sialidosis (OMIM # 256550)." (PMID 37686385, 2023). "These species, most likely, represent free oligosaccharides stored in the lysosomes of kidney tissues or secreted in the urine of Neu1-KO mice, since their corresponding human analogs were frequently identified in the urine of patients with sialidosis." (PMID 37698928, 2023). "In our previous study, we elaborated on the role of NEU1 in sialidosis and its role in AD via the immune system." (PMID 35847014, 2022). "The rarity of sialidosis and the unique biochemical nature of NEU1 are the main hindrances to developing an efficacious sialidosis treatment." (PMID 35847014, 2022).
sialidosis (continued). "Another critical aspect to consider is that although the catabolic role of NEU1 is profoundly crucial and remains central in the context of sialidosis." (PMID 35847014, 2022). "All in all, the advancement in the understanding of NEU1 activity being enhanced by environmental factors can be profoundly helpful in establishing a broader range of therapeutic interventions for sialidosis patients." (PMID 35847014, 2022). "In the present study, the authors have discussed various cellular mechanisms involving NEU1 and how they are relevant to sialidosis and Alzheimer’s disease." (PMID 35847014, 2022). "Homozygous Neu1−/− knockout mouse models display unique pathological phenotypes of sialidosis, but also share some clinical and histopathological features with galactosialidosis caused by a primary defect of the PPCA gene (chromosomal locus, 20q13.1)." (PMID 33922276, 2021). "Lysosomal exocytosis observed in NEU1 deficiency has been suggested to be deeply involved in the symptoms of patients with sialidosis and Neu1-KO mice, in contrast to other lysosomal diseases accompanied by lysosome expansion." (PMID 34188220, 2021). "Similar to other NEU1-deficient models, the expression of LAMP1 was markedly increased in the sialidosis-iNPCs (G227R-iNPCs and V275A/R347Q-iNPCs), compared with the normal-iNPCs." (PMID 33922276, 2021). "The Neu1-KO zebrafish was characterized by a smaller body size with the bending spine similar to patients with sialidosis and Neu1-KO mice." (PMID 34188220, 2021). "Sialidosis is a lysosomal storage disease (LSD) characterized by an abnormal accumulation of sialylated oligosaccharides and glycolipids resulting from NEU1 loss of function." (PMID 33922276, 2021). "This was accompanied by an equally significant increase of the corresponding residual enzyme activities and protein levels of the NEU1 mutant enzymes in all sialidosis type I fibroblasts." (PMID 32143456, 2020). "Mutations in NEU1 lead to deficiency in lysosomal neuraminidase (NEU1) and results in the glycoproteinosis termed sialidosis due to the accumulation of sialyated glycoconjugates." (PMID 32517081, 2020). "In line with this notion is the recent finding that the histone deacetylase (HDAC) inhibitor SAHA enhances NEU1 mRNA expression and NEU1 residual activity in fibroblasts from patients with both type I and type II sialidosis." (PMID 32143456, 2020). "Exploiting the chaperone role of PPCA on NEU1, we first tested the effect of rhPPCA on the residual activity of several mutant forms of NEU1 in sialidosis fibroblasts." (PMID 32143456, 2020). "ChIP performed with acetylated H3K14 antibody showed acetylation of the NEU1 promoter region also in sialidosis fibroblasts, confirming NEU1 transcriptional activation." (PMID 31399583, 2019). "KO mouse models of sialidosis (Neu1 KO) and galactosialidosis (Ctsa KO) develop phenotypes closely resembling severe systemic disease in human patients." (PMID 30088207, 2018). "Mechanisms of Pathogenesis in Sialidosis explained with the help of the Mouse Model: The Neu1−/− knockout (KO) mouse model is helpful in understanding the underlying molecular mechanism(s) of sialidosis." (PMID 29693572, 2018). "As already described in another case of sialidosis, both mutants showed reduced NEU1 protein levels by Western-blot analysis which correlate with the reduction in sialidase activity." (PMID 25153125, 2014). "Molecular defects in NEU1 are responsible for sialidosis, an inherited disease characterized by lysosomal storage disorder and neurodegeneration." (PMID 22952925, 2012). "NEU1 has been the first member of the family to be identified and the most studied, since its dysfunction is responsible for two genetic diseases, sialidosis (OMIM #256550) and galactosialidosis (OMIM #256540)." (PMID 22952925, 2012).
sialidosis (continued). "Because NEU1 and Trem2 are implicated in neurodegenerative/neuro-inflammatory diseases, including Alzheimer’s disease and sialidosis, modulating NEU1 activity may present a therapeutic approach to broadly regulate microglia-mediated neuroinflammation." (PMID 40943651, 2025). "In addition, the unique biochemical properties of NEU1 make it challenging to target it as an effective therapeutic option for sialidosis, which is a rare disease but has an enormous patient burden." (PMID 35847014, 2022). "Nevertheless, the neuropathological features characteristic of sialidosis, involving primary defects in the lysosomal and autophagic machinery, have not been fully elucidated across different NEU1 mutation types." (PMID 33922276, 2021). "At the age of 38, confirmatory genetic testing revealing a homozygous missense variant c.629C>T, p.Pro210Leu, in the NEU1 gene, previously not reported in patients with sialidosis nor found in large control databases (ExAC/gnomAD, dbSNP)." (PMID 34992946, 2021). "The enzymatic activity of NEU1 is activated/stabilized by cathepsin A. Cathepsin A dysfunctions due to mutations in CTSA (cathepsin A gene) causes galactosialidosis (OMIM # 256540), which is characterized by similar symptoms to those of sialidosis." (PMID 34188220, 2021). "So far, both SM/J and Neu1-KO mice have been used for sialidosis studies." (PMID 34188220, 2021). "Preclinical research conducted in Neu1 mutant mouse models revealed defects in virtually all systemic organs, including the nervous system and connective tissues that are similar or consistent with the clinical features of patients with sialidosis." (PMID 33922276, 2021). "Notably, lower protein levels of NEU1 were detected in the sialidosis-iNPCs (G227R-iNPCs and V275A/R347Q-iNPCs) compared to normal-iNPCs." (PMID 33922276, 2021). "Genetic defects of NEU1 trigger a sialidosis and impair the lysosomal catabolism of sialylated metabolites causing their accumulation, whereas inherited deficiencies of the stabilizing protein lead to a progressive accumulation of GM1, other glycolipids and oligosaccharides." (PMID 32272755, 2020). "Betaine treatment increased NEU1 mRNA levels in several of the sialidosis fibroblasts." (PMID 32143456, 2020). "Sialidosis (MIM 256550) is a rare, autosomal recessive inherited disorder, caused by α-N-acetyl neuraminidase deficiency resulting from a mutation in the neuraminidase gene (NEU1), located on 6p21.33." (PMID 29693572, 2018). "This aspect elucidates the fact that mutations affecting NEU1 activity can exist in the absence of other clinical signs that are characteristic of sialidosis." (PMID 29693572, 2018). "Interestingly, although various defects in macrophage populations have been described in Neu1-/- mice, and our study has now added insights into M1/M2 polarization, still the status of macrophages in sialidosis patients is currently unknown." (PMID 39346907, 2024). "An involvement of NEU1 in atherogenesis was further investigated in NEU1-deficient mice with cathepsin A hypomorph (CathAS190A‐Neo), which shows a 90% reduction in NEU1 activity without developing severe sialidosis-like phenotypes associated with complete NEU1 knockout mice." (PMID 36157440, 2022). "Interestingly, the hypomorph Ctsa mouse with secondary 90% deficiency of NEU1 does not develop sialidosis suggesting that 10% of residual enzymatic activity is sufficient to support the required rate of lysosomal SGC catabolism." (PMID 30088207, 2018). "Therefore, it is feasible to target Neu1 therapeutically without side effects associated with disruption of the intracellular sialidase activity, the known cause of sialidosis." (PMID 25187624, 2014). "However, mice with homozygous deletion of the Neu1 locus develop clinical abnormalities reminiscent of early-onset sialidosis in children, including severe nephropathy, progressive edema, splenomegaly, kyphosis and urinary excretion of sialylated oligosaccharides." (PMID 25187624, 2014).
sialidosis (continued). "The remaining six patients, not described in the literature, carry novel NEU1 mutations (p.Ala167Val, p.Tyr268Cys, p.Ser410Arg-fs), as well as a splice variant G > A at intron 3 + (g.1635G > A-fs), five of which in compound heterozygosity with mutations shared by other sialidosis patients." (PMID 32143456, 2020). "Although the mechanisms of muscle and bone dysfunctions in sialidosis have been clarified, the role of NEU1 in the regulation of emotional activity has not been explored to this day." (PMID 34188220, 2021). "NEU1 has been extensively studied as a target gene for sialidosis, but its role in the central nervous system has not been fully elucidated." (PMID 26731280, 2016). "Western blot analysis also showed that the protein expression levels of PPCA were not notably different between the normal- and sialidosis-iNPCs, suggesting that NEU1G227R and NEU1V275A/R347Q mutation-mediated loss of NEU1 activity is not correlated with PPCA expression." (PMID 33922276, 2021). "However, it has not been effective in sialidosis, attributable to the unique properties of NEU1." (PMID 35847014, 2022).
lysosomal storage disease (24 papers, 2012 to 2026). A metabolic disorder caused by mutations in proteins critical for lysosomal function, including lysosomal enzymes, lysosomal integral membrane proteins, and proteins involved in the post-translational modification and trafficking of lysosomal proteins. "A reduction in the enzymatic function of NEU1 results in the accumulation of sialic acid in various tissues, which is associated with several clinical manifestations indicative of lysosomal storage diseases." (PMID 40004480, 2025). "NEU1 deficiency is associated with sialic acid-rich macromolecular storage, leading to lysosomal disorder, sialidosis." (PMID 36973294, 2023). "This suggests that NEU1 deficiency is shared only by the lysosomal disorders that store HS." (PMID 40540388, 2025). "This PPCA–NEU1 interaction is essential for NEU1’s enzymatic role in the lysosome and is disrupted in lysosomal storage disorders such as galactosialidosis." (PMID 41301440, 2025). "Until 1977, deficiency of Neuraminidase 1 (NEU1) was thought to be associated with classical mucolipidosis I, a severe and rapidly progressive lysosomal storage disease with onset at birth or shortly after birth." (PMID 29693572, 2018). "Mutations in the CTSA gene, that encodes the protective protein/cathepsin A or PPCA, lead to the secondary deficiency of β-galactosidase (GLB1) and neuraminidase 1 (NEU1), causing the lysosomal storage disorder galactosialidosis (GS)." (PMID 23915561, 2013). "Finally, in addition to GRN, we found upregulation of other lysosomal genes frequently dysregulated in lysosomal storage disorders such as NEU1, NPC2, PSAP, CTSD, LAMP1, and HEXA." (PMID 38643236, 2024).
atherosclerosis (21 papers, 2015 to 2024). A disease characterized by the build-up of fatty material and calcium deposition in the arterial wall resulting in partial or complete occlusion of the arterial lumen. "Elastin-derived peptides (EDPs) constitute another risk factor for the development of atherosclerosis, whose atherogenic effects depend on sialidase activity and the NEU1/PI3Kγ signaling pathway as key regulators of its function in vitro and in vivo." (PMID 39194692, 2024). "The dysregulation of NEU1 function has been implicated in cardiovascular pathologies including atherosclerosis, vascular plaque inflammation, myocardial infarction, myocardial hypertrophy, heart failure, and diabetic cardiomyopathy (DCM)." (PMID 39194692, 2024). "In this study, NEU1-deficient (CathAS190A‐Neo), Neu3−/− or Neu4−/− mice were crossed with Apoe−/− mice, and atherosclerosis was evaluated." (PMID 36157440, 2022). "In an animal model of atherosclerosis, NEU1-deficient mice exhibited reduced monocyte and lymphocyte infiltration into atherosclerotic lesions compared with NEU1-sufficient mice." (PMID 35479093, 2022). "Animal models of human atherosclerosis were obtained in Neu4(−/−), Neu3(−/−), and NEU1-deficient (CathAS190A-Neo) mice." (PMID 35625910, 2022). "Interestingly, NEU-1 and the underlying activation of the PI3Kγ signaling pathway promote atherosclerosis onset in mice." (PMID 33920466, 2021). "Hence, an increase in NEU1 may cause chronic inflammation, resulting in the initiation and progression of several diseases such as cancers, rheumatoid arthritis, and atherosclerosis." (PMID 28420408, 2017). "In this complex, NEU-1 is essential for elastogenesis, signal transduction through this receptor and for biological effects of the elastin-derived peptides on atherosclerosis, thrombosis, insulin resistance, nonalcoholic steatohepatitis, and cancers." (PMID 38663826, 2024). "Collectively, NEU1 is closely related to inflammation and promotes the occurrence and development of atherosclerosis and HF." (PMID 35548408, 2022). "For instance, NEU1 potentiates airway inflammation in asthma, and upregulated levels of NEU1 potentiate inflammation in atherosclerosis." (PMID 36613682, 2022). "Monocyte recruitment and migration towards the intima is a crucial step in the pathogenesis of atherosclerosis and accompanied by macrophage NEU1 expression in human atherosclerotic plaques." (PMID 36009856, 2022). "Lowering Neu1 activity in CathAS190A-Neo Apoe(−/−) mice slowed down atherosclerosis progression, while the LDL levels remained intact." (PMID 35625910, 2022). "Overexpression of NEU1 promoted atherosclerosis development and plaque instability by enhancing pro-inflammatory cytokine expression." (PMID 34977042, 2021). "It was found that either 90% reduction in Neu1 activity or complete inactivation of Neu3 in Apoe(-/-) animals slowed down the progression of atherosclerosis." (PMID 34070542, 2021). "In monocytic and lymphocytic immune cells, NEU1 promotes atherosclerosis and plaque inflammation and thereby acts as a prerequisite for MI." (PMID 32975669, 2020). "NEU1 has been proposed to participate in the elastin degradation during vascular aging and provoke atherosclerosis." (PMID 25887273, 2015). "Since NEU1 was reported to highly expressed in macrophages in atherosclerosis vessels, we therefore speculated that NEU1 may also highly expressed in macrophages in AD vessels." (PMID 34869700, 2021).